ALK (ALK receptor tyrosine kinase)
Diseases named in the same sentence as ALK in open-access papers (continued):
Sharing a sentence is not in itself a finding about the gene and the disease.
tumor (continued). "Lastly, they observed significant differences in survival for patients with EGFR mutations compared to EGFR-WT (wild type) and EGFR pan-negative tumours, as well as ALK rearranged versus WT and ALK pan-negative tumours." (PMID 37686122, 2023). "Immunohistochemically (IHC), tumor cells were positive for SMA, MDM2, and p16; the cells were negative for desmin, MyoD1, Myogenin, pan-cytokeratin, S100, SOX10, HMB45, Malen-A, CD34, CD31, CD99, and ALK." (PMID 37735390, 2023). "Most of these patients showed a decrease in ALK VAF despite disease progression, suggesting underlying tumor heterogeneity and outgrowth of subclones without an ALK aberration." (PMID 37147298, 2023). "The combined analysis of PD-L1 and CD8+ TILs showed a significantly higher proportion of PD-L1-/TIL- tumours and a lower proportion of PD-L1+/TIL+ tumours in ALK-positive patients than in ALK-negative patients." (PMID 37371571, 2023). "ALK and EGFR are extremely effective targets in the process of tumor therapy." (PMID 36903251, 2023). "The study proposes a new approach based on hyperspectral image analysis to address the Anaplastic Lymphoma Kinase (ALK) positive and negative tumor identification problems." (PMID 36826944, 2023). "Tumor biopsy of the present case at diagnosis was only tested for EGFR, ALK and PD-L1, resulted in negative driver gene mutation." (PMID 38134118, 2023). "Similar results were obtained when analyses were performed in the population without known tumor EGFR/ALK alterations." (PMID 36928818, 2023). "Notably, combination of US Food and Drug Administration-approved ALK and PARP inhibitors markedly reduce tumor growth and improve survival of mice in PARP inhibitor-/platinum-resistant tumor xenograft models." (PMID 36253486, 2022). "The densities of stromal immune cells, including eTh cells, eCTL, and eTAM, as well as tumor PD-L1 expression, were also comparable between tumors with or without ALK rearrangement." (PMID 36233802, 2022). "In addition, IGF-1R has a synergistic effect on ALK signaling due to its protein Insulin receptor substrate 1 (IRS-1) which inhibits the IGF1R/IRS1 pathway and increases the sensibility of the tumor cells to ALK targeting." (PMID 34082691, 2022). "The CZB-treated mice presented a heterogeneous pattern, with some areas weakly positive for ALK staining, suggesting that CZB might impair ALK protein stability or that ALK protein might be regulated differentially within the single tumor cell population." (PMID 35351152, 2022). "Another rebiopsy revealed ALK:p.L1196M, but the tumor did not respond to brigatinib or carboplatin/pemetrexed, before stabilization under lorlatinib." (PMID 36207130, 2022). "Recently, it has been reported that, differently from ALK and RET, high wild-type ROS1 endogenous expression in normal tissue may obscure ROS1 3′/5′ EI detection in the tumor counterpart." (PMID 36612287, 2022). "Third, data on tumor mutation burden, including oncogenic drivers other than EGFR/ALK, were not reported." (PMID 35747163, 2022). "As stated in Methods, all patients with available tumor tissue sample were screened for mutations in the entire series of additional candidate genes (KRAS, ALK, BRAF, MET) regardless of the positive or negative result of the EGFR mutation testing." (PMID 35012520, 2022). "She had been diagnosed with lung adenocarcinoma with bone metastases; molecular analyses revealed that the tumor was negative for EGFR mutations and ALK gene rearrangements and that <1% of the tumor cells expressed PD‐L1." (PMID 35694999, 2022). "In addition, in our study, liquid biopsy highlighted 26 mutations, with the prevalence of ALK mutation in 96.6% of patients, supporting the idea that this approach could be an effective tool in cases with insufficient tumor tissue specimens or in cases where tissue specimens are not obtainable." (PMID 36422072, 2022). "ALK regulated VEGFA production and tumor angiogenesis in NSCLC, dependent on both HIF1α and HIF2α." (PMID 36012123, 2022).
tumor (continued). "Significant regulation of 8 out of 14 phosphosites (termed ‘oncogene addiction phosphorylation signature’, OAPS) that are modulated by METi in MET-addicted systems was detected also in EGFR-, ALK- and BRAF-addicted cellular tumor models following EGFR, ALK and BRAF targeting, respectively." (PMID 36494469, 2022). "Moreover, the simultaneous analysis of RNA extracted from the same samples allowed not only for the screening of fusion genes in specific tumor types (e.g., ALK and ROS1 fusions in NSCLC) but also in a tumor type agnostic setting (e.g., NTRK fusions)." (PMID 35626061, 2022). "As acquired resistance of targeting ALK in the advanced stage setting emerges inevitably, TKIs are able to inhibit cancer cell proliferation, hinder tumor growth, and control cancer metastasis, but not to eradicate or cure the disease." (PMID 35463328, 2022). "Interestingly, in ALK+ ALCL stem cells, crizotinib more potently induced autophagy and enhanced tumor cell resistance to the drug, an effect mediated by MYC." (PMID 35211406, 2022). "Lastly, several studies included molecularly selected subsets encompassing a small percentage of patients in the relevant tumor type (MSI-H and ALK+), which could limit the generalizability of the results." (PMID 35681656, 2022). "Functional interactions of the ALK+ ALCL cells with bone marrow stroma cells lead to fibroblast activation (CAFs) and alter the cytokine profile of the TME, which may contribute to tumor aggressiveness and possibly resistance to treatment." (PMID 35740600, 2022). "Out of the 34 pre-treatment ALK-rearranged NSCLC tumor specimens, 18 (53%) lacked vimentin expression and 16 (47%) expressed vimentin." (PMID 35042943, 2022). "With the development of tumor-related small-molecule targeted therapy, a second-generation ALK-TKI alectinib significantly increased the median PFS (25.7 vs. 10.4 months) than crizotinib in the first-line treatment of ALK-positive NSCLC." (PMID 35734411, 2022). "It is reported that tumor PD-L1 expression was also involved in the poor response to ICI-based therapy in ALK+ tumors, but the results of previous studies were not consistent." (PMID 36233802, 2022). "Nevertheless, the proportion of EGFR+/ALK+ patients with at least 25% of tumor cells expressing PD-L1 who achieved an objective response was not substantially lower than that in EGFR−/ALK− patients (12.2% vs 16.4%)." (PMID 35958559, 2022). "Further targeted systemic therapy is limited to non-resectable advanced stage patients with tumor genetic alterations such as ALK (anaplastic lymphoma kinase), MET (Met proto-oncogene), RET Ret proto-oncogene), and ROS1 (c-ROS proto-oncogene 1)." (PMID 35448189, 2022). "Collectively, the experience from these studies suggests that ALK represents a clinically actionable target in selected patients with ALK alterations irrespective of tumor type and cell lineage." (PMID 36337169, 2022). "Moreover, in the adenocarcinoma histotype, ALK, ROS1 and tumor proportion score (TPS) PD‐L1 assessment by IHC was possible in 96% (140/146) of cases, and molecular profile was obtained in 93.8% (137/146) of cases." (PMID 35868633, 2022). "Unlike tumor cells, all CTCs were found to be positive for ALK rearrangements, demonstrating an aggressive type of tumor cells." (PMID 36139444, 2022). "Baseline characteristics across sintilimab, pembrolizumab, atezolizumab, and nivolumab registration studies in the first-line treatment of nonsquamous NSCLC without EGFR or ALK genomic tumor aberrations." (PMID 35756655, 2022). "Accordingly, the downregulation of CD147 resulted in lack of expression of its downstream target MMP7 and correlated with lack of engraftment of ALK+ ALCL cells or striking tumor growth retardation." (PMID 35676454, 2022). "In addition, active ALK can phosphorylate SMAD4 at Tyr95, disable the DNA-binding activity of SMAD4 and then abrogate TGF-β-mediated tumor suppression responses." (PMID 36167821, 2022).
tumor (continued). "Among them, the rates of programmed death-receptor ligand-1 (PD-L1) tumor proportion score (TPS) ≥1% and ≥50% were 50% and 16%, respectively, and no significant relation between PD-L1 expression and ALK fusion variants was found." (PMID 35806042, 2022). "In ALK-positive ALCL patients, CD30 is continuously expressed in tumor cells." (PMID 35958559, 2022). "Neoplastic PD-L1 expression is consistently detected in ALK+ ALCL, while it is observed on the tumor cells of around 60% of ALK-negative ALCL cases." (PMID 35741318, 2022). "Several targeted therapies have been approved for the treatment of NSCLC harboring certain genetic variations in EGFR, ALK, ROS1, or BRAF and it is required to determine the existence of those genetic variations in tumor before targeted therapies are given to patients." (PMID 35061839, 2022). "ALK+ ALCL cases revealed a moderate to strong positive membranous staining in the majority of tumor cells, as opposed to the weak or absent staining observed in ALK− ALCL cases (histoscore 264.64+/− 40 vs 127.14+/− 105, p = 0.0001)." (PMID 35676454, 2022). "Alterations of ALK, NTRK, and NUT were identified in low frequencies in various tumor entities." (PMID 35204520, 2022). "Tumor samples of 248 patients with epidermal growth factor receptor (EGFR)/anaplastic lymphoma kinase (ALK)-negative non-squamous NSCLC treated with anti-PD-1 were molecularly tested by targeted next-generation sequencing or whole exome sequencing." (PMID 35592856, 2022). "In the last 15 years, molecular studies have highlighted the role e of genes called “Oncodrivers” involved in tumor genesis, particularly Epidermal Growth Factor Receptor (EGFR) and Anaplastic Lymphoma Kinase (ALK), which have become the target of specific and selective drugs." (PMID 35092185, 2022). "Patient characteristics were well-defined, with known negative status for EGFR and ALK genomic alterations of nonsquamous tumors and no missing data for tumor PD-L1 expression or patients’ performance status." (PMID 35205788, 2022). "In ALK+ ALCL, inhibition of autophagy facilitated tumor survival in the presence of ALK TKIs." (PMID 35211406, 2022). "There was a relatively large proportion of patients with unknown EGFR, ALK and ROS1 status in both cohorts and the tumour PD-L1 expression was unknown for many patients in the Post-1L IO cohort." (PMID 36139641, 2022). "Although molecular testing showed that the anaplastic lymphoma kinase (ALK) gene of the tumor did not undergo breakage and recombination, the histological and immunohistochemical findings were consistent with a diagnosis of IMT." (PMID 36460992, 2022). "When somatic variations occur, ALK is expressed in tissues that do not originally express ALK, and as such the cells are abnormally activated, resulting in uncontrolled cell proliferation and tumor formation." (PMID 35958559, 2022). "Eligible patients had untreated advanced nonsquamous NSCLC with a high tumor mutational burden (TMB) (tissue TMB >10 mutations per megabase or blood TMB ≥1.54 mutations per megabase) and without sensitizing EGFR or ALK alterations." (PMID 35498381, 2022). "ALK+ NSCLC often presents with central tumor location, large pleural effusion, and absence of a pleural tail." (PMID 35463328, 2022). "We hypothesized that samples in the dataset GSE19069, which are characterized by reduced ROR2 expression levels in ALK+ ALCL, were comprised of tissues with fewer tumor cell infiltrates." (PMID 35246138, 2022). "One limitation of our study is the fact that for all IHC-positive cases, not enough tumor material was available for further confirmation of ALK rearrangement by either FISH or NGS." (PMID 35756632, 2022).
tumor (continued). "Fourthly, tumor mutation-driver genes such as EGFR, ALK, and ROS1 and the use of targeted therapies were not recorded in the SEER data, and reflecting the time period of this study, neither were tumor PDL-1 status and the use of immunotherapy." (PMID 35847910, 2022). "After many years of research, ALK-TKIs have been used to treat NSCLC patients with the ALK mutant gene, which could inhibit the growth of tumor cells by inhibiting tyrosine kinase and thereby destroying the signaling pathway." (PMID 35370632, 2022). "Notably, combination of FDA-approved ALK and PARP inhibitors significantly suppressed tumor growth and prolonged animal survival in PARPi/platinum-resistant tumor xenograft models." (PMID 36284291, 2022). "Thus, the rational combination of ALK and PARP inhibitors holds great promise for expanding the utility of PARP inhibitors to many tumor types with HR proficiency." (PMID 36253486, 2022). "ALK+ ALCL expresses CD30, PD-L1, and B7-H3, which are potential therapeutic targets for promoting tumor cell death through pathways independent of ALK, thereby overcoming ALK TKI resistance." (PMID 35211406, 2022). "This may result in apoptosis of ALK TKI-resistant cells and the resensitization of tumor cells to crizotinib." (PMID 35211406, 2022). "In the ALK-rearranged NSCLC setting, liquid biopsy, mainly through ctDNA, progressively gained a routine application in the monitoring response to treatment and in early detection of tumor remission and molecular resistance to ALK-i." (PMID 36230686, 2022). "Very recently, FDA approved tremelimumab in combination with durvalumab and platinum-based chemotherapy for patients with metastatic NSCLC with no sensitizing EGFR, ALK genomic tumor aberrations." (PMID 36551630, 2022). "Treatment with the STAT5 SH2-domain inhibitor AC-4-130, results in a reduction in tumor growth in ALK+ ALCL, irrespective of PDGFRβ expression." (PMID 36045346, 2022). "Global STAT3 levels were unaffected by ALK expression, however, its activated form pSTAT3 was significantly increased upon ALK induction independent of tumor presence, suggesting an early role in the latent phase before tumor onset." (PMID 33310759, 2021). "YAP1 silencing suppressed tumor growth in resistant cells, patient-derived xenografts, and EML4–ALK transgenic mice, whereas YAP1 overexpression decreased the responsiveness of parental cells to the ALK inhibitor." (PMID 34685695, 2021). "Forced expression of EML4-ALK in mouse 3T3 fibroblasts resulted in subcutaneous tumors in nude mice, while oral administration of an ALK-directed tyrosine kinase inhibitor (TKI) resulted in rapid tumor regression." (PMID 33806977, 2021). "Consistent with the previous findings, ALK fusion-positive NSCLC tumor tissues, as well as negative ones, were confirmed to express hTERT." (PMID 33761896, 2021). "Edema Tumor Volume ratio on the other hand, was significantly associated with survival duration in the EGFR and KRAS mutation-positive groups, but not in ALK mutation-positive group." (PMID 33747933, 2021). "Compared to ALK‐negative patients, the ALK rearranged patients were younger, with more non‐smokers, more females, a larger primary tumor was demonstrated, and were a higher pathological stage." (PMID 34596344, 2021). "As previously reported, ALK-positive staining was not seen in the primary tumor cells, indicating the intratumor heterogeneity of ALK rearrangements in primary tumors." (PMID 34090412, 2021). "We have also provided evidence that this RU/RR dichotomy exists in ALK+ ALCL tumors, since the MYC expression level detectable by immunostaining is heterogeneous among tumor cells, and its level correlates significantly with that of active β-catenin, a marker of the activated Wnt canonical pathway." (PMID 34685497, 2021).
tumor (continued). "In this review, we have focused on the circuitry linking the oncogenic transcription factors MYCN and PHOX2B with their transcriptional targets ALK and LIN28B and the tumor suppressor microRNAs let-7, miR-34 and miR-204, which should act as down-regulators of their expression." (PMID 34771690, 2021). "The most plausible reason of ALK negative in the sample was that the tumour blocks accounted with a very few number of tumour cells." (PMID 34801049, 2021). "Patient characteristics, including age, gender, pack-years, race, tumor site, epithelial growth factor receptor (EGFR) status, anaplastic lymphoma kinase (ALK) status, kirsten rat sarcoma viral oncogene (KRAS) status, TNM stage, pathological stage, and gene expression, were collected." (PMID 33686947, 2021). "One study observed that PET-based radiomics combined with tumor stage and age was able to differentiate ALK/ROS1/RET fusion-positive and fusion negative tumors (sensitivity = 0.73, specificity = 0.70)." (PMID 34208595, 2021). "However, PD-L1+ tumour cells were frequently found in 34 of 45 ALK+ (76%) and 21 of 50 ALK− (42%) sALCL patients." (PMID 34742294, 2021). "As Rosa26_Alkal2;Th‐MYCN tumour‐derived NB cells are sensitive to ALK TKI inhibition, we tested whether NB tumour development could be inhibited in mice." (PMID 33411331, 2021). "Haematoxylin and eosin (HE) staining of the primary surgically resected tumour sample revealed typical adenocarcinoma histology with positive IHC markers including Napsin A, cytokeratin 7 (CK7), thyroid transcription factor‐1 (TTF‐1) and ALK (Ventana)." (PMID 34541785, 2021). "Therefore, the improved technique was also testedon sEVs isolated from PE-fluid samples of two NSCLC patients, PE002and PE011, having an ALK and EGFR-driven tumor, respectively." (PMID 34473477, 2021). "It has been reported as CD 2, 4, 30 and 56 positive and negative for CD 7, 8, TCL1 (tumor cell lysate), EBER (Epstein–Barr encoding region) and ALK (anaplastic lymphoma kinase)." (PMID 34066230, 2021). "ALK-translocated RCC is the prototype of a molecularly-defined RCC, because this tumor may show many morphological aspects." (PMID 34680535, 2021). "Thus, we suggest that our observation of ALK expression and phosphorylation in MCC tumor samples is genuine." (PMID 34029351, 2021). "In 2019, the indication for pembrolizumab was expanded as the first‐line treatment for advanced NSCLC patients with PD‐L1 expression (Tumor Proportion Score [TPS] ≥1%) and no EGFR or ALK mutations." (PMID 34977873, 2021). "On the other hand, this tumor is ALK-negative in approximately 40–50% of ALCL cases, and various molecular biological factors are involved in ALK-negative cases." (PMID 34503168, 2021). "In all eight BI-ALCLs, most of the tumor cells showed nuclear and occasional cytoplasmic staining, whereas the cALCL and ALK+ sALCL samples were negative." (PMID 34944796, 2021). "Both ALK-positive and ALK-negative tumors can be evaluated by PET scans as both tumor types uptake 18F-FDG in PET." (PMID 34441322, 2021). "ALK and EGFR rearrangements may co-occur in one and the same tumor specimen, and it is already known that compound EGFR mutations feature a more aggressive behavior." (PMID 33572278, 2021). "In the era of molecularly driven therapies, offering sequential targeted treatment options in ALK and ROS1-positive NSCLC, re-characterization of the tumor via repeated biopsies has become an established procedure and was carried out in 50% of patients in the routine setting." (PMID 33613692, 2021). "Based on the results of IMpower150, ACPB regimen was approved by the U.S. FDA in 2018 for the first‐line treatment of advanced nonsquamous NSCLC with no EGFR or ALK genomic tumor aberrations." (PMID 34977873, 2021). "Interestingly, restoration of STAT5A and IL2RG expression has been reported to impair NPM/ALK expression in ALCL cells, thus acting as tumor suppressors in this context." (PMID 34503232, 2021).